IL18 (interleukin 18)
Diseases named in the same sentence as IL18 in open-access papers (continued):
Sharing a sentence is not in itself a finding about the gene and the disease.
colitis (continued). "By contrast, another study showed that caspase-1 KO mice had increased susceptibility to DSS-induced colitis, and the severity of colitis was associated with a decrease in IL-18 production." (PMID 33143375, 2020). "IBD is also associated with SNPs in CARD-9, and mice lacking CARD-9 or the kinase Syk show reduced inflammasome activation and IL-18 secretion during azoxymethane (AOM)–DSS-induced colitis-associated colon cancer." (PMID 33119702, 2020). "Of note, the administration of antifungal drugs rendered wild type mice highly susceptible to AOM/DSS-induced colitis-associated colorectal cancer, and supplementation with IL-18 rescued their predisposition to colorectal cancer." (PMID 30717382, 2019). "Transgenic mice deficient in IL-1β, IL-18 or both cytokines protected against TNBS colitis induction in mice." (PMID 31139196, 2019). "In a colitis model, IL-18 acted directly on intestinal epithelial cells to enhance inflammation, thereby exacerbating colitis via excessive IL-18 stimulation in IL-18BP-deficient mice." (PMID 30717382, 2019). "The other topic is the importance of fungi in microbiota for protection against colitis-associated colorectal cancer by inducing IL-18." (PMID 30717382, 2019). "For example, caspase-11-deficient mice revealed a hypersensitivity to dextran sulfate sodium-induced colitis associated with an impeded IL-18 production, suggesting an ameliorating effect of caspase-11 during intestinal inflammation." (PMID 30670931, 2018). "Further studies have demonstrated that Nlrp1b deficiency in mice was associated with reduced colonic levels of Il-18 and Il-1β with a concomitant increased colitis susceptibility and CAC development upon DSS- and AOM-DSS treatment." (PMID 29868004, 2018). "Loss of IL-18 bp expression is associated with severe colitis and loss of mature goblet cells in mice." (PMID 30227886, 2018). "For this reason we are unable to examine their phenotype in the mouse model of DSS-induced colitis, and instead we genetically deleted the gene encoding IL-18 on the Il-1r−/−Nlrp1aQ593P/Q593P background." (PMID 30214011, 2018). "This shows that IL-18 signaling after Nlrp1 activation increases the disease severity of DSS-colitis, associated with increased IFNγ-producing Th1 cells." (PMID 30214011, 2018). "Studies with NLRP6 knockout mice have shown that increased Prevotellaceae and decreased IL-18 levels are associated with colitis." (PMID 28796169, 2017). "Conversely, independent studies using IL-18- and IL-18R-deficient mice revealed a beneficial role for IL-18 signaling during DSS colitis." (PMID 28979266, 2017). "This conclusion is further supported by studies showing that IL-18 KO or IL-18R KO mice are also highly susceptible to DSS-induced colitis and AOM/DSS-induced colon cancer." (PMID 28955343, 2017). "Deficiency in NLRP6 and IL-18 has also been linked to colitis-related colorectal cancer (CRC) development." (PMID 26925061, 2016). "Others have shown that 2,4,6-trinitrobenzene sulfonic acid (TNBSA) was unable to induce significant colitis in IL-18 deficient mice and that administration of an IL-18 neutralizing antibody resulted in a dramatic attenuation of mucosal inflammation." (PMID 26355424, 2015). "Somewhat surprisingly, only IL-18−/− mice but not IL-1β−/− or IL-1R−/− mice are more susceptible to chemical-induced colitis, suggesting that IL-18 is a major contributor to microbiota homeostasis." (PMID 25879288, 2015). "In agreement with the findings in Casp1−/− mice, NLRP6-deficient mice had impaired IL-18 production mainly from the intestinal epithelial compartment further diminishing the capacity of these mice to recover from colitis." (PMID 25071785, 2014). "To determine the physiological relevance of our proposed pathway, we examined Rip2-deficient mice for IL-18 production and inflammasome activation in the colon during C. rodentium induced colitis." (PMID 25254654, 2014).
colitis (continued). "Nlrp3, Asc and Caspase-1/11 KO mice are also hyper-sensitive to acute DSS colitis, with low colonic IL-18 levels associated with disease susceptibility, while administration of exogenous IL-18 ameliorates colitis severity." (PMID 23847622, 2013). "IL-18-deficient mice, for instance, have increased inflammation and tumor development in a colitis-associated colon cancer model." (PMID 23606794, 2013). "To determine whether MC-dependent adverse events have similar underlying immune mechanisms, we compared the IL-18 plasma levels of patients with the cutAE subtype urticaria to patients with T-cell-driven cutaneous AEs and colitis." (PMID 38539560, 2024). "Mice deficient in either NLRP3/6, CASP1 or IL-18 show exacerbated response to DSS-induced colitis." (PMID 38163085, 2023). "The ability of Inflammasome sensors, such as NLRP3, to mediate the secretion of IL-18, a cytokine that contributes to epithelial barrier repair against damage, is a mechanism that explains the protective role of IL-18 against colitis-associated colorectal cancer." (PMID 36902104, 2023). "In animal studies, increased expression of IL-18 was linked to exacerbation of colitis, and blocking IL-18 signalling can reduce inflammation and alleviate symptoms in models of IBD, highlighting the importance of IL-18 as a target for new drugs for IBD treatment." (PMID 38031150, 2023). "Similarly, in Caspase-1 deficient mice, the severity of DSS induced colitis was suppressed correlating with IL-18 reduced expression." (PMID 36032110, 2022). "It was shown that an IL‐18 transgene produced increased susceptibility to DSS‐induced colitis." (PMID 33491282, 2021). "In the same light, IL18 has been implicated as a dual role cytokine in colitis, and it was proposed that the anti-inflammatory effects of IL-18 may be observed in the early stages of colon inflammation." (PMID 35008767, 2021). "IL-18 is a multifunctional cytokine; IL-18 offers protection against colitis, with a deficiency in IL-18 proposed to predispose the host to inflammation associated with colitis and epithelial damage." (PMID 34071220, 2021). "To determine whether GSDMD exacerbates colitis pathology by inducing IL-18 release, we injected intraperitoneally Gsdmd-deficient mice at a concentration of 1 μg recombinant mouse IL-18 per mouse daily during DSS colitis." (PMID 34721422, 2021). "Moreover, an activating mutation of NLRP1 aggravated DSS-induced colitis, which was associated with an enhanced Th1 response and an increased IL-18/ IFNγ production in the gut." (PMID 33808793, 2021). "Recently, a series of studies have pointed out that IL-18 can provide protection against colitis and/or colitis-associated cancer, and IL-18 deficiency may predispose the host to chemically induced colitis." (PMID 30873162, 2019). "In fact, IL-18 KO or IL-18R KO mice are also highly sensitive to colitis-associated CRC." (PMID 30609850, 2019). "Card9−/− mice and mice selectively deficient for Syk in myeloid cells were predisposed to azoxymethane (AOM)/DSS-induced colitis-associated colorectal cancer, concomitant with reduced mature IL-18 in colon explants and an impaired accumulation of anti-tumorigenic T cells in the colon." (PMID 30717382, 2019). "Moreover, we demonstrate that increased IL-18 is associated with an increased Th1 response during DSS-induced colitis, while loss of Nlrp1 prevents this, and leads to increased butyrate-producing commensals from the Clostridiales order." (PMID 30214011, 2018). "Moreover, an activating mutation in Nlrp1a increases IL-18 and IFNγ production, and decreases colonic butyrate to exacerbate colitis." (PMID 30214011, 2018). "Consequently, IL-18 KO mice are more susceptible to the dextran sulfate sodium (DSS)-induced colitis." (PMID 29601578, 2018). "Similarly, non-hematopoietic NLRP6 expression was found to be necessary to protect against DSS colitis, an effect that was again associated with impaired IL-18 production." (PMID 28979266, 2017).
colitis (continued). "However in Aim2-deficient mice with DSS-induced colitis, IL-18 is enhanced through other mechanisms, which subsequently lead to sustained activation of STAT3 and Akt pathways." (PMID 28360909, 2017). "Additionally, administration of recombinant IL-18 can induce remission in colitis-associated injuries and suppress the progression of colorectal tumor in Nlrp3/Caspase1-deficient mice." (PMID 28360909, 2017). "As IL-1 and IL-18 are main inflammatory mediators processed by inflammasomes, it remains unclear how the host immune system integrates IL-1 and IL-18 signals during colitis and inflammation-associated colon cancer." (PMID 28955343, 2017). "In addition, caspase-1−/− animals were more susceptible to DSS-mediated colitis, which was associated with decreased epithelial cell proliferation and IL-18 secretion." (PMID 28979266, 2017). "Importantly, colitis was clearly reduced in IL-18-deficient mice up to 18h p.i., while cecum luminal colonization appeared stable throughout the course of infection." (PMID 27341123, 2016). "However, in models of colitis-associated colorectal cancer IL-18 cytokine add-back showed that IL-18 protected against tumor." (PMID 26378020, 2015). "Interestingly, mice deficient in caspase-11 are also susceptible to DSS-induced colitis, but independently of IL-1β and IL-18 secretion, suggesting the existence of a mechanism distinct from classical inflammasome function in the gut." (PMID 26483605, 2015). "Indeed, mice deficient in NLRP3, NLRP6, NLRC4, ASC, caspase-1, and IL-18 are susceptible to DSS-induced colitis." (PMID 26483605, 2015). "Consistently, recent reports further emphasize that IL1R, IL18R or IL18 deficiency renders mice highly susceptible to DSS-induced colitis indicating that signaling through MyD88 is required to preserve the intestinal barrier and to promote repair following injury." (PMID 24886810, 2014). "Moreover, it has been shown that Il18−/− or Il18r−/− mice are more susceptible to DSS-induced colitis and CRC, mimicking the increased tumor burdens observed in NLRP3 and caspase-1 deficient mice." (PMID 25071785, 2014). "Moreover, transgenic over-expression of IL-18 is associated with exacerbated colitis, which displays a marked infiltration of mucosal macrophages." (PMID 23847622, 2013). "In contrast, IL‐18 may protect against colitis/colitis‐associated cancers." (PMID 40671401, 2025). "Moreover, metabolites, including butyrate and nicotinic acid, from these microorganisms serve as mediators of G-coupled receptor-109a-dependent induction of IL-18 in the colonic epithelial cells, along with the dampening of colitis and colitis-associated tumorigenesis." (PMID 38617537, 2024). "Moreover, wt mice co-housed with Il-18 but not with Il-1β or I1-1R deficient mice had an increased susceptibility to DSS-induced colitis suggesting that the colonic defect in Il-18 is the major downstream event responsible of enhanced colitogenic microbiota in Nrp6−/− mice." (PMID 29868004, 2018). "Similarly, Aim2−/− mice showed an impaired Il-1β and Il-18 synthesis associated with an overgrowth of colonic E. coli and an increased risk of developing colitis which may be counteracted by Il-18 infusion." (PMID 29868004, 2018). "Moreover, injection of recombinant IL-18 could ameliorate the severity of DSS-induced colitis in inflammasome-deficient mice." (PMID 28955343, 2017). "Blocking IL-1α with FLO1 mAb (a murine-specific monoclonal antibody) markedly reduced ileitis/colitis severity, while paradoxically elevating IL-18 (a gut barrier integrity promoter) and inflammatory markers." (PMID 40661957, 2025). "Collectively, these findings demonstrate that IL-18 plays a pivotal role in mediating the exacerbation of DSS-induced colitis by inulin." (PMID 41133791, 2025).
colitis (continued). "In vivo, administration of an IL-18BP alleviated DSS-induced colitis and single knockout of IL-18 (as well as double knockout together with IL-1β) protected against dinitrobenzene sulfonic acid (DNBS)-induced colitis." (PMID 40869366, 2025). "Atranorin administration protected against NLRP3 inflammasome-driven diseases and ameliorated colitis in vivo by improving epithelial barrier function and reducing IL-1β and IL-18 production." (PMID 40869366, 2025). "IL-18 KO mice fed with a cellulose enriched diet and those fed with an inulin-supplemented diet exhibited similar levels of DSS-induced colitis severity, as indicated by comparable weight loss, colon length, and colon weight." (PMID 41133791, 2025). "Although these microbial changes do not induce inflammation under normal conditions, they exacerbate intestinal inflammation in the context of DSS induced colitis through the activation of innate immune cells and the IL-18/MyD88-dependent signaling pathways." (PMID 41133791, 2025). "Our finding strengthens the reports of previous studies improving the severity of DSS-induced colitis mice models by inhibiting the IL-18 activity." (PMID 40224484, 2025). "Collectively, our findings suggest that inulin intake exacerbates DSS induced colitis through microbiota-mediated inflammation and MyD88/IL-18 signaling, with the effects persist in the offspring." (PMID 41133791, 2025). "Conversely, using the FLC functional blocker peptide F991 significantly reduces activated IL-1β, IL-18, and activated caspase-1, while alleviating colitis progression and decreasing tumorigenesis." (PMID 40806736, 2025). "To clarify the functional role of IL-18 in inulin-aggravated DSS-induced colitis, we used IL-18 knockout (KO) mice that were cross-fostered with wild-type (WT) mice to normalize their gut microbiota." (PMID 41133791, 2025). "Modulating the Treg/Th2 response by decreasing proinflammatory cytokines such as TNFα, IL-6, IL-1β, IL-18, IL-22, IL-9 and increasing anti-inflammatory cytokines IL-10 and IL-4 in mice colitis model." (PMID 41208998, 2025). "IL-18 is a crucial cytokine involved in the pathogenesis of colitis, playing both pro-inflammatory and anti-inflammatory roles depending on the stage and context of the disease." (PMID 41340115, 2025). "Together, these results demonstrate that colitis in KI mice was significantly ameliorated following IL-18 blockade and continued to improve over time, even after drug withdrawal." (PMID 41116055, 2025). "This cascade, including inflammasome engagement, leads to the overproduction of the pro-inflammatory cytokine IL-18, a key mediator of colitis, which in turn drives tissue damage and exacerbates intestinal inflammation." (PMID 41133791, 2025). "DCL (5 and 10 μg/kg) markedly inhibited DSS‐induced increase of ASC puncta formation, IL‐1β and IL‐18 secretion in colons of colitis mice." (PMID 40919130, 2025). "Among these cytokines, interleukin-18 (IL-18) has been identified as a critical molecular mediator in the pathogenesis of colitis." (PMID 41133791, 2025). "The plasma levels of IL-18 in urticaria patients are similar to those with colitis, the second most common irAE under ICI." (PMID 38539560, 2024). "Histamine produced by microbiota dysbiosis in the colon suppresses NLRP6 inflammasome assembly, IL-18, and its downstream anti-microbial peptide expression, thus exacerbating dextran sodium sulfate-induced colitis." (PMID 38791713, 2024). "The NLRP1 inflammasome also plays a protective role in the development of colitis-associated CRC, which is associated with the release of the effector cytokines IL-1β and IL-18." (PMID 39684769, 2024). "After DSS-induced colitis we detected statistically significant increases in IL-22 and IL-18 concentration and insignificant but clearly visible trend in increase of IL-6 and IL-12p40." (PMID 39354587, 2024).
colitis (continued). "On the contrary, the study conducted by Siegmund and co-workers reported that a caspase-1 deficit in DSS-induced colitis mice had protective effects on the evolution of the disease, related to the limited production of IL-1β and IL-18." (PMID 39684769, 2024). "The deletion of IL18 or IL18 receptor (IL18R) in IECs induces protection from colitis and maintains barrier integrity in mice, which indicates that IL18 is crucial in driving the pathogenesis of inflammation-induced colitis." (PMID 39767678, 2024). "During inflammation-induced colitis, IL-18 prevents the development of goblet cells from uncommitted precursors, significantly reducing mucus production and intestinal barrier function." (PMID 39769266, 2024). "The absence of AIM2 affected caspase-1 activation and the production of IL-1β and IL-18, whilst also making mice highly susceptible to DSS-induced colitis associated with microbial dysbiosis." (PMID 39684769, 2024). "NLRP1 activation can exacerbate DSS-induced colitis, relating to enhanced Th1 response and increased IL-18/IFNγ production in the intestine." (PMID 38455052, 2024). "The inhibition of IEC-derived IL18 is important to maintain the mucus layer and intestinal barrier function in colitis." (PMID 39767678, 2024). "Metabolites produced by the gut microbiota, including butyrate and niacin, can mediate Gpr109a-dependent interleukin (IL)-18 induction in the colonic epithelium, suppressing colitis and colon cancer." (PMID 38322318, 2024). "Experiments have shown that inflammasomes weaken the occurrence of colitis and colitis-related tumors in mouse models, the effector factor IL-18 plays a key role in this action." (PMID 37553473, 2023). "In contrast, inhibition of IL-18 has also been shown to exert protective effect in experimental colitis models." (PMID 37910490, 2023). "PA/CCMTS-P showed excellent anti-inflammatory effects both in vitro and in vivo, which obviously reduced the secretion of TNF-α, IL-6, IL-1β, and IL-18 after LPS stimulation in Raw264.7 cells, and the expression of IL-1β and IL-18 at the colitis site in vivo." (PMID 36843930, 2023). "The administration of free recombinant IL-18 reduced colitis in mice, supporting protective functions of IL-18 in colitis." (PMID 37891577, 2023). "To confirm this, we also used IL18 knockout (KO) and their littermates to observe the effects of IL18 deficiency on KLPJ-mediated colitis." (PMID 36436756, 2023). "Recent studies suggest a dual role of IL-18 in colitis through the regulation of the function and quantity of goblet cells." (PMID 37383609, 2023). "These components play a role in the NLRP3 inflammasome activation, which drives intestinal inflammation in colitis by consequent production of IL-1β and IL-18." (PMID 37513865, 2023). "Moreover, DSS-treated mice administered concurrently with l-clodronate show milder clinical symptoms of colitis, intestinal transit times similar to control animals, and decreased expression of factors implicated in neural inflammation and death, including Bax, Hdac4, IL-18, Casp8 and Hif1a." (PMID 38105266, 2023). "A study investigating the mechanistic role of IL-18 in colitis induced by dextran sulfate sodium (DSS) used a DSS-induced colitis mouse model to examine its functional role." (PMID 38162651, 2023). "The secretion of mature IL18 in the colon after exposure to KLPJ was much higher than in the control group, suggesting that KLPJ-mediated colitis occurs through IL18." (PMID 36436756, 2023). "We showed that KLPJ-mediated colitis occurred through the caspase-11–mediated release of mature IL18 in the gut epithelial cells, which plays an important role in the induction of IFNγ production, increasing NK cell activity and T-cell proliferation." (PMID 36436756, 2023). "Blocking IL-18 is effective in attenuating disease damage in animal studies, including dextran sulphate sodium-induced colitis, collagen-induced model of arthritis, and nephritis of MRL/lpr mice." (PMID 38031150, 2023).